DPP4 (dipeptidyl peptidase 4)
Diseases named in the same sentence as DPP4 in open-access papers (continued):
Sharing a sentence is not in itself a finding about the gene and the disease.
tumor (341 papers, 2003 to 2026). "This downregulation of DPP4 represents an active mechanism of immune evasion, by which tumor cells exploit LKB1 deficiency to suppress pathways critical for immune activation." (PMID 41283988, 2025). "Investigators found that DPP-4 is well expressed in tumor cells and is associated with metastasis and poorer clinical outcomes." (PMID 38611003, 2024). "Membrane expression of DPP4-positive cancer cells is associated with increased tumor invasion and chemotherapy resistance." (PMID 39247602, 2024). "Patients on both DPP4 inhibitors and metformin, which has also been associated with tumor suppression, had even more pronounced of a survival advantage, suggesting a synergistic effect (HR: 0.83; 95% CI: 0.77-0.90; p < 0.0001)." (PMID 34055551, 2021). "Preclinical studies have reported that DPP-4 inhibitors potentially increase the risk of tumor metastasis." (PMID 34063285, 2021). "There is evidence demonstrating the potential modulatory functions of DPP4 in the immune system and its association with tumor initiation and progression." (PMID 34298800, 2021). "A functional analysis of tumor-associated proteins revealed reduced expressions of several proteinases, including dipeptidyl peptidase 4 (DPP4), carboxypeptidase E (CPE) and prostate specific antigen (KLK3) in AG and metastatic PCa." (PMID 34556748, 2021). "Gene markers of M1 macrophages showed weak correlations, whereas M2 macrophage markers showed moderate and strong correlations with DPP4 expression, revealing the potential regulatory role of DPP4 in the polarization of tumor-associated macrophages." (PMID 33614513, 2021). "For instance, high expression levels of CD26/DPP4 were significantly associated with advanced tumor stages in a cohort of CRC patients and with reduced overall and disease-free survival." (PMID 34885056, 2021). "A functional analysis of tumor-associated proteins revealed the reduced expression of several proteinases, including dipeptidyl peptidase 4 (DPP4), carboxypeptidase E (CPE) and prostate specific antigen (KLK3), particularly in AG and metastatic PCa." (PMID 34556748, 2021). "The serine protease dipeptidyl peptidase 4 (DPP4) plays key roles in metabolism and immunity, and its expression has been associated with either pro- or anti-tumour effects in multiple tumour types." (PMID 33143089, 2020). "As for clinical relevance, DPP-4 expression in tumor specimens is associated with increased serum DPP-4 activity, more advanced clinical stages, and poor prognosis in HCC patients." (PMID 31969650, 2020). "Carriers of DPP4 mutations are considered appropriate and valuable indicators of long-term cardiometabolic and tumor outcomes of DPP4i and incretin mimetic drugs during T2DM treatment." (PMID 29556215, 2018). "In some tumors, such as astrocytoma, gastrointestinal stromal tumors, and some lymphomas, overexpression of DPP4 is associated with tumor aggressiveness." (PMID 27936466, 2017). "High expression of DPP4 in UBUC significantly associated with higher tumor pT stage (p < 0.001), presence of nodal metastasis (p = 0.033), vascular invasion (p < 0.001) and perineural invasion (p = 0.021)." (PMID 27936466, 2017). "Recent studies have identified CD26/ dipeptidyl peptidase 4 (DPP4) as a gene that affects the invasiveness of many tumor cells and it is consistently associated with cancer." (PMID 26471376, 2015). "LKB1 loss strongly correlated with a reduction in DPP4 levels in tumor cells (P = 0.0364)." (PMID 41283988, 2025). "Fusing DPP4 with an anti-tumor-associated antigens nanobody enables the specific degradation of intratumoral sICOSL, prevents off-target side effects, but could be hard to penetrate into the tumor due to large molecular weight." (PMID 40708008, 2025). "As a ferroptosis-related gene, DPP4 was associated with tumor aggression." (PMID 38331878, 2024). "MMP1 promotes tumor-associated angiogenesis and metastasis by regulating DPP4 expression." (PMID 39247602, 2024).
tumor (continued). "Moreover, we conducted bioinformatic studies to highlight the clinical significance of DPP4 expression and mutation in various types of malignancies, as well as the invasion of different immune cells into the tumor microenvironment." (PMID 37624423, 2023). "The DPP4 rs7608798 and rs2268889 polymorphisms may be pivotal markers to predict PCa tumour aggressiveness and prognosis." (PMID 37533175, 2023). "We suggest that DPP4+ASCs play a tumor-promoting role in cancers associated with VAT." (PMID 37454080, 2023). "Interestingly, in a model of lung metastasis, NK cytolytic ability against tumor cells was decreased in DPP4-deficient mice." (PMID 36213442, 2022). "Interestingly, we found that the mRNA expression levels of DPP4/CTNNB1/MET are inversely associated with tumor purity." (PMID 35205190, 2022). "As DPP4 is closely associated with tumor immunity, it might because of the diminished immune response at terminal stage of tumor patients." (PMID 33614513, 2021). "Seemingly, the underlying mechanisms of DPP4-mediated anti-tumor immune modulation could be different across tumor types (and maybe across mouse models)." (PMID 31482487, 2019). "Besides, high expression of DPP4 was associated with some clinicopathological factors, including larger sizes of tumor, lymphatic metastasis, higher TNM stages, higher recurrence rate and unfavorable histological type." (PMID 30038597, 2018). "This could partially explain our results, as UC with higher levels of DPP4 frequently associated with high histological grading and advanced tumor pathological (pT) staging." (PMID 27936466, 2017). "Furthermore, tumor-associated activation factors Dpp4 and Fapα are generally up-regulated in older fibroblasts compared to the 3 month controls." (PMID 21912590, 2011). "Consistent with these context-dependent effects, Zuo and colleagues demonstrated that the DPP4 inhibitor anagliptin could be synergized with anti–PD-L1 therapy, as it reprogrammed tumor-associated macrophages, further underscoring that DPP4 function can vary with tumor context." (PMID 41283988, 2025). "Importantly, evidence has manifested that DPP4 overexpression in PTC is closely associated with tumor invasion and may serve as a potential prognostic marker for PTC." (PMID 38890707, 2024). "Thus, DPP4 loss in RCC secretome may lead to the increased availability of CXCL10 for MSCs stimulating their migration toward tumor." (PMID 37563650, 2023). "Consequently, our analysis of tumor immune infiltrating cells within the TME of THCA tumor revealed that the high expression levels of the DPP4/CTNNB1/MET signature correlate positively with the infiltration levels of tumor-associated macrophages, regulatory T cell, and cancer-associated fibroblast." (PMID 35205190, 2022). "While distinct reports indicate an increase in incidence rates of selected cancers, other studies argue against an association of tumor incidence and CD26/DPP4 inhibition and some analyses even indicate that CD26/DPP4 inhibition might instead improve outcomes related to certain tumor types." (PMID 34885056, 2021). "Our data provide direct evidence reinforcing the notion that EMT is associated with tumor immune inhibition, whereby Snail could serves as a transcription factor of DPP4, which induces local immunosuppression by negatively regulating lymphocyte trafficking via cleavage of the chemokine CXCL10." (PMID 32430013, 2020). "DPP4-reconstituted H2122 cells significantly accelerated the migration of NK-92 cells from the side channels toward the tumor spheroids." (PMID 41283988, 2025). "DPP4 plays a dual role in modulating antitumor immunity by acting as both a promoter and suppressor of immune responses, depending on the tumor context and immune microenvironment." (PMID 41283988, 2025). "As for microenvironment of lung metastases, paclitaxel also downregulated DPP4 in tumor cells, NK cells, macrophage and DCs, indicating more complicated effect of paclitaxel in the lung." (PMID 40708008, 2025).
tumor (continued). "The reanalysis of a scRNA-seq dataset also showed that EZH2i increased almost the Dpp4 expression of all tumor-infiltrating immune cells." (PMID 40708008, 2025). "Conclusively, it’s confirmed that cytotoxic drugs such as paclitaxel induced DPP4 expression in the tumor cells to block the degradation of sICOSL and stabilize ICOS in T cells." (PMID 40708008, 2025). "Recently, it was shown that the protease DPP4 reduces the infiltration of lymphocytes by cleaving and inactivating CCL5 and CXCL10 and that the inhibition of DPP4 improves tumour control and synergises with immune checkpoint therapies (ICBs)." (PMID 40579444, 2025). "The combination of osimertinib and sitagliptin, a DPP4 inhibitor, not only suppressed tumor progression but also reduced the number of residual tumor cells and minimal residual disease." (PMID 40479551, 2025). "While osimertinib monotherapy reduced the number of tumor cells in the MRD tissues, the number of DPP4‐positive tumor cells showed a significant increase." (PMID 40479551, 2025). "In summray, EZH2 inhibitor enhances tumor response to chemoimmunotherapy through DPP4-sICOSL pathway." (PMID 40708008, 2025). "Further investigation is warranted to elucidate how DPP4 functionally shapes the tumor–immune microenvironment." (PMID 41283988, 2025). "In support of its clinical relevance, analysis of publicly available datasets via GEPIA revealed that CD26 (DPP4) expression is significantly upregulated in tumor tissues compared to normal tissues in both colon and rectum adenocarcinomas." (PMID 40806753, 2025). "Its surface expression has also been detected on tumor cells, where DPP4 can exhibit dual roles, acting either as a tumor promoter (e.g., in pleural mesothelioma) or as a tumor suppressor (e.g., in melanoma and neuroblastoma)." (PMID 40597436, 2025). "The DPP4-reconstituted H2122 cells significantly accelerated the migration of CD8+ T cells from the side channels toward the tumor spheroids, similar to the effects observed with NK-92 cells." (PMID 41283988, 2025). "The positive rate of DPP4 in the tumor cells of MRD after osimertinib treatment was much higher than that of xenograft tumors before treatment." (PMID 40479551, 2025). "By regulating biopeptide activity, DPP-4 cleaves peptides, cytokines, and chemokines, which are essential to the tumor microenvironment." (PMID 40282969, 2025). "To address this issue, we have developed nanobody-DPP4 fusion proteins that can specifically degrade sICOSL, achieving substrate selectivity and tumor targeting." (PMID 40708008, 2025). "We also assessed tumor cell–specific DPP4 and LKB1 protein levels using IHC in a panel of 57 patient-derived NSCLC samples, which were enriched for KRAS mutations." (PMID 41283988, 2025). "The dCas9-HDAC fusion protein has been used in further studies to target the DPP4 promoter, reducing histone acetylation, inhibiting DPP4 (Dipeptidyl peptidase-4) expression and significantly reducing tumor growth and metastasis." (PMID 40600050, 2025). "The combination of osimertinib and sitagliptin resulted in a greater reduction in GPF‐positive tumor cells and a concurrent decrease in DPP4, Nrf2, and CPT1A expression." (PMID 40479551, 2025). "Dpp4, the gene encoding the CD26 receptor that is necessary for adenosine deaminase activity, was upregulated in Ptger4-KO and Ptges-KO tumor cells." (PMID 39298269, 2024). "Results demonstrated that DPP4 and Ki67 expression in tumor tissues was suppressed by miR-570-3p overexpression and elevated by miR-570-3p knockdown." (PMID 38890707, 2024). "DPP4 has also been demonstrated to interact with the tumor microenvironment, suggesting its essential role in CRC." (PMID 38203779, 2024). "The differentially expressed GPR65, DPP4, and CXCR6 are involved in the anti-cancer efficacy of PD-1 blockade by affecting the recruitment of tumor-associated macrophages or CD8 + T cells." (PMID 38698468, 2024).
tumor (continued). "Proteolytically active CD26/DPP4 is also present on plasma exosomes derived from both tumor cells and T cells, having the capacity to ligate potential interaction partners, but knowledge of them is also scarce." (PMID 39001488, 2024). "DPP4/CD26 was identified as a marker of senescence in fibroblasts, and it has been described as a tumour promoter and tumour suppressor in various types of cancers." (PMID 38786063, 2024). "A previous study examining the impact of specific DPP4 inhibition in murine cancer models has demonstrated that DPP4 inhibition not only elevates tumor CXCL10 levels but also enhances the trafficking of CXCR3+ NK cells and CD8+ T cells into tumors." (PMID 38672409, 2024). "The results showed that the expression of IPCEF1, TFF3, GLT8D2, TPO and DIO1 were downregulated in the tumor group and DPP4, LRP4, CDH3, KCNJ2, CLDN1, GABRB2, FN1 were upregulated in the tumor group." (PMID 39513122, 2024). "Further investigation showed that IL-33 is not only an inducer of CCL11 production and a protector against DPP4, but it also increases eosinophil-mediated tumor cytotoxicity." (PMID 37587450, 2023). "In particular, data obtained from Chip-seq and luciferase reporter assays showed that circMET overexpression induced an immunosuppressive tumor microenvironment via the miR-30-5p/Snail/DPP4/CXCL10 axis." (PMID 37958352, 2023). "We also confirmed the tumour‐suppressive role and prognostic effect of DPP4 in PCa using PCa clinical samples and PCa cell lines." (PMID 37533175, 2023). "SUV39H1 inhibition results in DPP4 upregulation and ferroptosis induction, suggestive of tumor suppressive DPP4 role." (PMID 37563650, 2023). "Based on the TCGA, GEO and CPTAC databases, we found a significant decrease in DPP4 expression in OV tumor tissues compared to control tissues." (PMID 37907650, 2023). "There is longstanding evidence indicating a tumour‐promoting or ‐suppressive role of DPP4 in different cancer types." (PMID 37533175, 2023). "Based on the TCGA and GTEx databases, GEPIA2 analysis showed a decrease in DPP4 mRNA expression in OV tumor tissues." (PMID 37907650, 2023). "circMET overexpression induced an immunosuppressive tumor microenvironment through the sponging of miR-30-5p and the upregulation of Snail, which induced dipeptidyl-peptidase-4 (DPP4) expression." (PMID 37958352, 2023). "DPP4-positive findings were observed in the subcutaneous tissues (stroma) of all transplanted tumor tissues, including the parental SCCVII cells." (PMID 37218983, 2023). "The literature describes that DPP4 act as a tumor suppressor gene and was downregulated in some types of cancer." (PMID 37371512, 2023). "Next, we assessed connections of these four DPP4 genetic variants with PCa clinicopathologic features, including PSA levels at diagnosis, clinical T (cT) stage, pathologic T and N stages, tumour invasion statuses and D'Amico classification." (PMID 37533175, 2023). "This difference in the anti-tumor effects of IFN-inducible chemokines was suggested to be dependent on the sensitivity to DPP4/CD26, an enzyme that cleaves chemokines expressed in tumor tissues." (PMID 37218983, 2023). "CXCL12 not only binds to CXCR4, but also to CXCR3 and DPP4 on tumor cells in our study, which is consistent with previous reports." (PMID 37719863, 2023). "Several preclinical studies have demonstrated that DPP-4 inhibitors have anti-inflammatory and profibrotic effects, and even anti-tumor effects in various organs." (PMID 37669959, 2023). "In our study, we found that the DPP4 inhibitor, anagliptin, combined with anti-PD-L1 antibody enhanced the tumor-suppressive effect of PD-L1 blockade on NSCLC." (PMID 37115489, 2023).
tumor (continued). "DPP-4 inhibitor KR treatment revealed a significant decrease in the p62-positive area and apoptotic tumor cells compared to that of the control tumor." (PMID 37760498, 2023). "DPP4‐knockdown by small interfering (si)RNA in vitro led to suppression of tumour growth through cell cycle arrest in HCC cell lines, suggesting that DPP4 has a pro‐oncogenic role in HCC." (PMID 37533175, 2023). "Suppression of the catalytic activity of chemokines stimulated by DPP4 can thereby inhibit tumour cell proliferation." (PMID 37148547, 2023). "An important finding of this study was the involvement of DPP4, a membrane-bound serine protease, in the differential anti-tumor effects of IFN-induced chemokines." (PMID 37218983, 2023). "The results from the GSE26712 and GSE18520 datasets also showed downregulation of DPP4 expression in OV tumor tissues." (PMID 37907650, 2023). "To explore the cause of this difference in the anti-tumor effects of IFN-induced chemokines, we performed IHC studies on the expression of DPP4 in tumor tissues." (PMID 37218983, 2023). "Taken together, these data demonstrated that DPP4 levels were decreased in OV patients (both in tumor tissues and serum)." (PMID 37907650, 2023). "The gene CD26 should be overexpressed if we look for the metastatic potential of CSCs in tumors, as was confirmed for the serum protein levels, DPP4 enzymatic activity, and gene transcription in the tumor." (PMID 36230486, 2022). "have demonstrated that the increased expression of dipeptidyl peptidase 4 (also known as CD26) has been observed in mouse and human tumours and is associated with worse survival." (PMID 35344301, 2022). "A study involving lung cancer patients has revealed that the expression levels of β-catenin correlate with DPP4 expression and contributed to tumor metastasis." (PMID 35205190, 2022). "The DPP4 inhibitor, vildagliptin prevented tumor progression by suppressing the proangiogenic role of CCL2 but did not affect VEGF, VEGF receptor 2 or angiopoietin-1 levels." (PMID 35053615, 2022). "The angiogenesis-associated proteases Plat (tPA) and Dpp4 (DPP4), as well as the membrane serine protease Fap (FAP or seprase), which can be selectively expressed by tumor pericytes, were amongst the serine proteases overexpressed in the QZ1-hi population." (PMID 36192379, 2022). "An immunosuppressive tumor microenvironment regulated by the miR-30-5p/Snail/dipeptidyl peptidase 4 (DPP4)/CXCL10 axis was demonstrated in vivo." (PMID 35186039, 2022). "To validate their expressions, we used the UALCAN online bioinformatics tool with default settings, which showed that mRNA levels of DPP4/CTNNB1/MET were higher in THCA tumor tissues compared with adjacent normal tissues." (PMID 35205190, 2022). "In particular, the essential role of DPP4 in the tumor microenvironment and antitumor immunity is of intense interest." (PMID 36467461, 2022). "DPP4 expressed higher in advanced tumor stage groups, Stage 2 vs. Stage 3 (p < 0.01) and Stage 2 vs. Stage 4 (p < 0.001)." (PMID 36467461, 2022). "CD26/DPP4 is a membrane-bound protein, and its higher expression has been found in a wide variety of tumor pathologies." (PMID 36071454, 2022). "Hollande and colleagues emphasised the role of CCL11 by demonstrating that dipeptidyl peptidase DPP4 (CD26) inhibitor sitagliptin led to enhanced tumor control through enhanced CCL11-mediated eosinophil recruitment at the tumor site." (PMID 35563461, 2022). "The inhibition by sitagliptin and vildagliptin of exosomal DPP4 derived from 5-fluorouracil-resistant colon cancer cells suppresses tumour growth and angiogenesis in vivo." (PMID 35158891, 2022). "Some new interactions have been observed between MDSCs and mature osteoclasts or progenitor osteoclasts in tumor tissues, suggesting that MDSCs are recruited to tumor tissues (CCL3L1_CCR1, CXCL2_DPP4 and CCL3L1_DPP4)." (PMID 36466840, 2022).